TTR (transthyretin)
Diseases named in the same sentence as TTR in open-access papers (continued):
Sharing a sentence is not in itself a finding about the gene and the disease.
amyloidosis (continued). "The siRNA drug, Patisiran, is approved for a rare polyneuropathy caused by hereditary transthyretin-mediated (hATTR) amyloidosis and works by binding and degrading the messenger RNA transcript for transthyretin." (PMID 31156715, 2019). "Hereditary transthyretin amyloidosis is a rare, autosomal dominant disease caused by mutations in the TTR gene encoding transthyretin, a T4-thyroid hormone and retinol transport protein." (PMID 31452021, 2019). "By using a one-step procedure without pre-purification (direct MALDI), within 30 min we successfully detected variant TTR Val30Met in addition to WT TTR in serum samples from ATTRv amyloidosis patients with a heterozygous TTR Val30Met mutation." (PMID 31133063, 2019). "The most frequent TTR variant is TTR V30M that causes ATTRV30M amyloidosis (formerly designated familial amyloid polyneuropathy (FAP))." (PMID 30875761, 2019). "Although the current understanding of the molecular pathophysiology underlying TTR amyloidosis is still incomplete, it is widely regarded that tetramer dissociation into monomers is the initial and consequential step in its amyloidogenesis." (PMID 30934952, 2019). "The clinical phenotype of variant TTR amyloidosis varies greatly by its mutation, age of onset, disease penetrance and prognosis." (PMID 31001136, 2019). "The best known phenotypes are the neuropathic and cardiac ones, with the V30M (p.V50M) mutation being the most common TTR variant described worldwide, comprising 73% of all hATTR amyloidosis cases." (PMID 31399774, 2019). "Transthyretin amyloidosis (ATTR amyloidosis) is a fatal systemic disease caused by amyloid deposits of misfolded transthyretin, leading to familial amyloid polyneuropathy and/or cardiomyopathy, or a rare oculoleptomeningeal amyloidosis." (PMID 31001136, 2019). "Transthyretin (TTR) amyloidoses (ATTR amyloidosis) are diseases associated with transthyretin (TTR) misfolding, aggregation and extracellular deposition in tissues as amyloid." (PMID 30875761, 2019). "To date, more than 140 different mutations in the TTR gene have been reported, most of which have been associated with ATTRv amyloidosis." (PMID 31133063, 2019). "More than 100 different TTR variants are associated with ATTRm amyloidosis, of which the V30M mutation is the most common and prevalent in Japan, Portugal and Sweden." (PMID 30704121, 2019). "Transthyretin amyloidosis (ATTR) is the most common type of autosomal-dominant hereditary systemic amyloidosis associated with the transthyretin (TTR) protein; with either early- or late-onset presentation in patients." (PMID 31001136, 2019). "In ATTRwt amyloidosis, the misfolding of TTR is associated with age (formerly called senile systemic amyloidosis, SSA), mainly affecting the heart, although it has a systemic distribution." (PMID 31359320, 2019). "Familial amyloid polyneuropathy (FAP) or ATTRv (amyloid TTR variant) amyloidosis is a fatal hereditary disease characterized by the deposition of amyloid fibrils composed of transthyretin (TTR)." (PMID 31253122, 2019). "The mechanisms responsible for the fibrillization of TTR in ATTRm amyloidosis are the consequence of one of over 100 TTR mutations with several variants that often exhibit tissue-selective deposition and pathology." (PMID 30704121, 2019). "Transthyretin (TTR) – a transport protein implicated in amyloidosis – was also up-regulated in the mid-coronal section by 2-fold." (PMID 29632138, 2018). "Transthyretin-related hereditary amyloidosis (ATTR) is a systemic disease characterized by extracellular deposits of amyloid due to the autosomal dominant inheritance of a mutation in the TTR gene (18q12.1)." (PMID 29970125, 2018). "Transthyretin (TTR) amyloidosis is a systemic disorder caused by extracellular deposition of insoluble amyloid fibrils in peripheral and autonomic nerves, heart, kidney, gastrointestinal tract, and other organs." (PMID 30553273, 2018).
amyloidosis (continued). "Hereditary amyloid TTR (ATTR) amyloidosis is an autosomal dominant disease in which gene mutations lead to changes in the protein TTR." (PMID 30553273, 2018). "Evidences suggest that transthyretin (TTR), a plasma protein associated with transthyretin amyloidosis or familial polyneuropathy (FAP) interacts with heterologous amyloid proteins including amyloid beta and islet amyloid polypeptide." (PMID 29593496, 2018). "TTR-related amyloidosis can be inherited in the case of genetic mutations or can be nonhereditary when it is due to wild-type (WT-TTR)." (PMID 29967786, 2018). "Small interfering RNAs and ASOs have been developed for the treatment of transthyretin (TTR) amyloidosis, a progressive heart disease causing severe congestive heart failure." (PMID 30090066, 2018). "Considering that the total population in Mexico by 2017 is estimated at approximately 123.5 million inhabitants., Amyloidosis due to TTR mutations for Mexico would have a rate of 0.89 cases per 100,000." (PMID 29970125, 2018). "All forms of amyloidosis associated with the TTR gene are progressive, encompassing a variable life expectancy that is thought to be dependent on the mutation of the gene, although certain factors have been described that modify its expression." (PMID 29970125, 2018). "Aggregates of mutated and wild type TTR are responsible for various TTR amyloidoses, and treatment options currently being tested include genetic strategies to knock down synthesis of the protein." (PMID 30111340, 2018). "Hereditary ATTR V30M amyloidosis is a lethal autosomal dominant sensorimotor and autonomic neuropathy caused by deposition of aberrant transthyretin (TTR)." (PMID 28539873, 2017). "It is worth to emphasize, that trans-suppressor mutations of TTR are of considerable interest, because they can be potentially employed to treat TTR-related amyloid diseases using liver targeted gene therapy." (PMID 28338000, 2017). "Pathogenic mutations associated with inherited TTR amyloidosis make the protein more susceptible to aggregation." (PMID 28338000, 2017). "Even though there are more than a 100 mutations causing ATTR amyloidoses, the first discovered and by far the most common is ATTR V30M, which is due to a substitution of a valine with methionine in position 30 (Val30Met) of the TTR protein." (PMID 28539873, 2017). "The most striking example of this inter-population diversity is the Val30Met mutation [rs28933979, c.148G > A, p.Val50Met], which is one of the leading causes of TTR amyloidosis." (PMID 28335735, 2017). "In general, amyloidosis can be classified as primary,secondary, related to dialysis and associated with transthyretin." (PMID 28678923, 2017). "The monomer-monomer interface is pointed out as one of the most vulnerable regions to mutations that lead to significant changes in the TTR-tetramer equilibrium dynamics and, therefore, induces TTR amyloidosis." (PMID 28704493, 2017). "An alternative treatment for some types of amyloidosis would be livertransplantation with the goal of replacing the mutated TTR gene that producesthe majority of the circulating transthyretin by a gene found in a geneticallynormal donor organ." (PMID 28678923, 2017). "Magnetic resonance imaging appears as another alternative for the diagnosis ofcardiac amyloidosis, with a sensitivity of 87% and specificity of 96% for theform associated with TTR." (PMID 28678923, 2017). "ATTR V30M amyloidosis is caused by extracellular accumulation of misfolded transthyretin (TTR), subsequently creating insoluble aggregates of amyloid fibrils." (PMID 28539873, 2017). "Our data further indicate that in the absence of C1q there is marked reduction of macrophages in association with amyloid deposits and thus less effective phagocytosis of TTR." (PMID 28407005, 2017). "Ageing and mutations of transthyretin (TTR), the thyroid hormones and retinol transporting protein lead to amyloidosis by destabilizing the structure of TTR." (PMID 27501389, 2016).
amyloidosis (continued). "TTR gene mutation is known to be associated with amyloid diseases, and low levels of TTR in the CSF have also been found to be associated with some neurological disorders such as schizophrenia." (PMID 26752631, 2016). "In vitro, tolcapone binds with high affinity and strongly inhibits the aggregation of WT-TTR as well as the kinetically unstable V122I-TTR variant, involved in cardiac TTR amyloidosis." (PMID 26902880, 2016). "Crystal structures of tolcapone bound to wild-type TTR and to the V122I cardiomyopathy-associated variant show that it docks better into the TTR T4 pocket than tafamidis, so far the only drug on the market to treat TTR amyloidoses." (PMID 26902880, 2016). "Our findings stimulate to novel strategies in future drug development against TTR-associated amyloidoses." (PMID 26108284, 2015). "Mutations and aging cause misfolding to result in TTR amyloidosis, and pharmacological chaperone therapy has successfully been used to treat both forms." (PMID 26664897, 2015). "TTR amyloidosis predominantly affecting the heart is particularly associated with the Val122Ile variant, which is very rare in Caucasians but is carried by 4% of African-Americans." (PMID 26400472, 2015). "Wild-type and variant forms of transthyretin (TTR), a normal plasma protein, are amyloidogenic and can be deposited in the tissues as amyloid fibrils causing acquired and hereditary systemic TTR amyloidosis, a debilitating and usually fatal disease." (PMID 26400472, 2015). "In vitro, TTR monomers can undergo partial unfolding allowing self-aggregation and ultimately polymerization into fibrils causing amyloidosis." (PMID 26437390, 2015). "Subpial TTR amyloid deposits were associated with brisk superficial reactive gliosis and siderosis in the neocortex and cerebellar cortex." (PMID 26156087, 2015). "Transthyretin-mediated amyloidosis is an inherited, progressively debilitating disease caused by mutations in the transthyretin gene." (PMID 26338094, 2015). "Hereditary transthyretin amyloid (ATTR) amyloidosis or familial amyloid polyneuropathy (FAP) is a rare autosomal dominant disease caused by mutated transthyretin (TTR)." (PMID 25908211, 2015). "Few TTR variants preferentially affect the central nervous system, manifesting as oculoleptomeningeal amyloidosis." (PMID 26156087, 2015). "More than 100 point mutations in human TTR result in TTR amyloidosis (familial amyloidotic polyneuropathy)." (PMID 25784853, 2015). "Flies expressing the mutated TTRV30M display an impaired neurological phenotype that resembles the clinical manifestations of TTR-associated amyloidosis in humans similarly to the published model with TTR V14N/V16E." (PMID 26020516, 2015). "In transthyretin amyloidosis, where transthyretin misfolds to cause disease, compounds have been developed to stabilise the protein as a functional tetramer." (PMID 25653875, 2015). "The amyloidogenic variants L55P, V122I, V30M and wild-type TTR, which itself is amyloidogenic in senile TTR amyloidosis, become susceptible to proteolytic cleavage and disassembly of the truncated protomer under increasing shear stress." (PMID 26286619, 2015). "Several in vitro studies have demonstrated that the TTR tetramer dissociation and consequent formation of amyloid fibrils are necessary processes to cause amyloidosis." (PMID 26558262, 2015). "Natural fibrils of apolipoprotein A-I mainly contain the N-terminal polypeptide corresponding to the first 100 residues, and the presence of transthyretin (TTR) fragments can be considered almost a hallmark of the cardiac involvement in TTR amyloidosis." (PMID 25750126, 2015). "Early-onset familial cases are associated with devastating amyloidosis diseases such as transthyretin familial amyloid polyneuropathy (TTR-FAP), which is characterized by pain, muscular weakness and autonomic dysfunction." (PMID 24396149, 2014).
amyloidosis (continued). "Two main forms exist: hereditary and wild-type transthyretin amyloidosis, the former associated with transthyretin gene mutations." (PMID 24767411, 2014). "Familial forms of TTR-related amyloidosis are inherited in an autosomal dominant manner and arise from single point mutations in the coding sequence of the TTR gene." (PMID 23390551, 2013). "Familial amyloid polyneuropathy (FAP) is an autosomal dominant disease characterized by deposition of amyloid related to the presence of mutations in the transthyretin (TTR) gene." (PMID 23387326, 2013). "SSA is caused by the aggregation of wild-type protein (WT-TTR), primarily in the heart, and more than 100 different point mutations are associated with the other three TTR-related amyloidoses." (PMID 24358189, 2013). "To confirm that SAP has a role in the pathogenesis of TTR-associated amyloidosis, we performed a genetic study in transgenic Drosophila melanogaster." (PMID 23390551, 2013). "Attention has recently focused on the relatively rare leptomeningeal form of TTR amyloidosis, which is induced by several point mutations in the TTR gene and also found in the advanced stages of Val30Met TTR-FAP." (PMID 23425518, 2013). "With a goal of establishing a diagnostic center for TTR-related amyloidoses, our groups have established the protocols for sequencing TTR genes and offer this service to the population of the State of Rio de Janeiro and to the Brazilian people in general." (PMID 24358189, 2013). "Patients with stage 0 disease are asymptomatic but have both a variant form of the TTR gene and evidence of amyloid deposits." (PMID 23425518, 2013). "TTR amyloidosis is the most common form of hereditary (familial) amyloidosis, and is caused by mutations that destabilize the TTR protein." (PMID 23425518, 2013). "TTR misfolding and aggregation are associated with amyloid diseases such as senile systemic amyloidosis, familial amyloid polyneuropathy and familial amyloid cardiomyopathy (Rochet & Lansbury, 2000 ▶; Buxbaum & Tagoe, 2000 ▶; Kelly, 1996 ▶; Benson, 1989 ▶)." (PMID 24121323, 2013). "To determine the role of SAP in TTR-induced toxicity, we complemented the in vitro studies with a genetic approach in a Drosophila model for TTR-associated amyloidosis." (PMID 23390551, 2013). "Until now, more than a hundred point mutations have been described in the TTR gene as the cause of three types of TTR-related amyloidoses (FAP, FAC and CNSA), which occur early in life." (PMID 24358189, 2013). "FAP is an autosomal-dominant inherited form of amyloidosis, mostly associated with mutations of the transthyretin gene, with a prevalence higher than previously estimated." (PMID 23853716, 2013). "TTR is associated with two amyloidoses: senile systemic amyloidosis (SSA) and familial amyloid polyneuropathy (FAP)." (PMID 23466880, 2013). "At least 27 different human proteins are known to cause amyloidosis, the best known being the Aβ peptide (which is associated with Alzheimer’s disease), prion protein, and transthyretin (TTR)." (PMID 23390551, 2013). "Rate-limiting tetramer dissociation and rapid monomer misfolding and disassembly of TTR lead to amyloid fibril formation in different tissues causing various amyloid diseases." (PMID 22973437, 2012). "There is, however, a wide variation of 5-year survival rates for patients with different TTR mutations (30–55 %) and among patients with wild-type TTR amyloidosis (40–75 %)." (PMID 22584381, 2012). "Apart from its function as a carrier of T4 and retinol, TTR has taken more recently a very important role in amyloidogenic diseases and it is one of the 30 human proteins associated with amyloidosis, in particularly FAP." (PMID 23028965, 2012). "Hereditary transthyretin amyloidosis or familial amyloidotic polyneuropathy (FAP) is a dominantly inherited transthyretin amyloidosis that is caused by mutated transthyretin (TTR)." (PMID 22897426, 2012).
amyloidosis (continued). "For example, the rare L55P mutation produces a more aggressive amyloidosis than the more common V30M mutation, and in-vitro studies show that L55P TTR aggregates more much readily than V30M TTR." (PMID 21375738, 2011). "To investigate the link between amyloidogenesis and tissue targeting of protein aggregates in vivo, we established a Drosophila model for TTR-associated amyloidosis." (PMID 21179560, 2010). "Transthyretin is known to be associated with the amyloid diseases senile systemic amyloidosis (SSA), familial amyloid polyneuropathy (FAP), and familial amyloid cardiomyopathy (FAC)." (PMID 20498702, 2010). "Transthyretin associated amyloidosis includes two differential diagnosis, senile cardiac amyloidosis and familial amyloid polyneuropathy." (PMID 20142933, 2008). "In the case of amyloid disease due to mutations affecting transthyretin, Kelly and coworkers have proposed that the amyloidogenic partially-unfolded intermediate is generated during degradation in the lysosome." (PMID 18253099, 2008). "In individuals with TTR pathogenic variants over the age of 30 years old with at least 2 visits (n=802), we extracted diagnostic codes for heart failure, cardiomyopathy, amyloidosis, polyneuropathy, and carpal tunnel syndrome to capture well-established features of hATTR." (PMID 41282679, 2025). "Likewise, the transthyretin amyloidosis model demonstrated reduced pathogenic TTR protein deposition." (PMID 40465697, 2025). "The hereditary form for amyloidosis is ATTRm, which is caused by mutations in the TTR gene." (PMID 41010872, 2025). "ATTR-wt amyloidosis, caused by aging-related misfolding of the wild-type TTR protein." (PMID 41295360, 2025). "Furthermore, in cases of transthyretin mutation, it can be deposited in the kidneys and cause a condition called amyloidosis." (PMID 40564893, 2025). "Hereditary transthyretin (ATTRv) amyloidosis is a rare, progressive, fatal disease caused by misfolded transthyretin (TTR) protein that accumulates as amyloid fibrils in multiple organs, particularly nerves and heart, but also in the eyes, the central nervous system, and kidneys." (PMID 40903555, 2025). "Old age can also cause TTR amyloidosis of which wild type TTR fibres are found in the heart." (PMID 40367241, 2025). "A Capillary Zone Electrophoresis (CZE) fragment screening methodology was developed and applied to the human plasma protein Transthyretin (TTR), normally soluble, but could misfold and aggregate, causing amyloidosis." (PMID 40367241, 2025). "A variant of the TTR gene may also predispose the eldest affected sibling to autosomal dominant hereditary TTR amyloidosis." (PMID 41296379, 2025). "Non-human primates, such as aged vervet monkeys carrying the human TTR-Val122Ile allele, spontaneously develop cardiac arrhythmias and fibril deposits, providing a physiologically faithful—but logistically challenging—model for wild-type amyloidosis." (PMID 41295360, 2025). "However, the efficacy of tafamidis is reduced for patients with TTR amyloidosis diagnosed at a later stage, when severe organ damage caused by TTR aggregates cannot be reversed." (PMID 40816471, 2025). "Our hypothesis to explain this result is that the emergence of new biotherapies specifically targeting ATTRv amyloidosis has prompted clinicians to test patients for TTR variants." (PMID 40260709, 2025). "The NM_000371.4:c.424G>A; p.(Val142Ile) variant in TTR (HGNC:12405) is thought to have reduced penetrance compared to other variants that contribute to TTR-related hereditary transthyretin amyloidosis and the Grpmax FAF is approximately nine times the relevant BS1." (PMID 41000626, 2025). "The higher prevalence of TTR variants identified supports the greater awareness for TTR amyloidosis in Portugal, allowing for early diagnosis, follow-up, and treatment, including liver transplant, pharmacotherapy, and an implantable cardioverter-defibrillator when indicated." (PMID 40332002, 2025).